RET (ret proto-oncogene)
Diseases named in the same sentence as RET in open-access papers (continued):
Sharing a sentence is not in itself a finding about the gene and the disease.
cancer (continued). "However, that there is a precedent for functional and therapeutically actionable EGFR, MET, and BRAF kinase domain duplications in other cancers is suggestive that a similar mechanism may be applicable to the observed RET kinase duplications in breast cancer." (PMID 30446652, 2018). "It has been demonstrated that a combined analysis of somatic RET and Ki-67 is useful for identifying patients with a more aggressive cancer, and their joint assessment could ameliorate the initial risk stratification of patients with sporadic MTC, and thus be of prognostic relevance." (PMID 28676824, 2017). "Indeed, some small molecules agents analyzed in this study were mainly multikinase-inhibitors (e.g. vandetanib: EGFR VEGFR RET) or substances (e.g. thalidomide) which affected a lot of cellular processes and antiangiogenesis was only part of anti-cancer mechanisms." (PMID 27901478, 2017). "Thus, both the oncogene RET and the RET receptor tyrosine kinase may contribute to cancer development." (PMID 27092013, 2016). "Thus, the common structure shared by the three compounds may represent a novel scaffold to generate potent and selective type II TKIs for cancers that exhibit constitutively active RET signaling." (PMID 26046350, 2015). "Our group and others have recently demonstrated that PNI may be facilitated by neural secretion of GDNF, which phosphorylates the RET tyrosine kinase receptor when coupled with the GFRα receptor and triggers downstream signaling pathways that promote cancer cell migration and invasion." (PMID 22768171, 2012). "Thus, RET inhibitors were recently developed for specific human cancer therapies." (PMID 23300832, 2012). "A search for predicted nonsynonymous mutations in a set of 138 genes that are known to be mutated by single-base substitutions and indels in human cancers yielded heterozygous single-base substitutions in RET and FANCD2 that were not present in either of the two normal genomes that we sequenced." (PMID 22341448, 2012). "A total of 1,501 distinct fusions in at least one of the nine driver genes assessed (ALK, RET, ROS1, NTRK1/2/3, FGFR2, FGFR3, and NRG1) were detected in 1,497 patients for a combined prevalence of 2.2% across the pan-cancer cohort." (PMID 41091579, 2025). "RET gene fusions have been reported as driver genes for various types of cancer, including thyroid, lung, intestine, pancreas, and breast, and fusions such as CCDC6-RET, NCOA4-RET, and KIF5B-RET are known to be frequently seen." (PMID 40647546, 2025). "Given that proto-oncogenes such as MYC, KRAS, RET, and VEGF are often overexpressed in human cancers, we analyzed the regulatory effect of BTO-28 on proto-oncogene transcription in HT-29 cells." (PMID 40966493, 2025). "Another, methods for decrease cancer diseases spreading are inhibition the enzymes responsible for cancer multiplicity and spreading like DHFR, CDK2, RET, TULBIN, HSP90, HSP70, EGR...etc." (PMID 39985107, 2025). "Currently, six pan-cancer biomarkers—NTRK, BRAF V600E, RET, HER2-positive, MSI-high, and TMB-high—along with nine molecularly targeted therapies have expanded treatment options across diverse malignancies." (PMID 40576713, 2025). "For PDAC neuroinvasion, PanCIA identified interaction between Schwann cell GDNF and cancer cell RET activating the PI3K/AKT pathway, advancing the “RET inhibitor + neurocleansing” regimen into Phase II trials." (PMID 41463034, 2025). "Rearrangement of TBL1XR1 (3q26.32) have been identified in various cancers involving different genes, including RARA (17q21), HMGA1 (6p21), TP63 (3q28), RET (10q11.2), and PIK3CA (3q26.32)." (PMID 41123735, 2025). "Aberrant activation of RET leads to the activation of multiple downstream pathways, including RAS/MAPK, PI3K/AKT, PKA, and PKC, driving cancer development." (PMID 41244832, 2025).
cancer (continued). "We analyzed 8,805 3’ kinase gene fusions curated from the COSMIC, focusing on the seven most common kinase fusions involving ALK, RET, ROS1, NTRK1, NTRK3, ABL1, and BRAF genes found in various types of cancers." (PMID 38877018, 2024). "For example, APOE, PLAU, CDK1 and MUC1 were significantly higher in TNBC tissues than in cancer-parasite tissues, whereas PDGFRB, RET, ROCK2, CCND1 and PPARA were significantly lower in TNBC tissues than in cancer-parasite tissues." (PMID 38329441, 2024). "Recently, CNTN1 has been reported to mediate cell functions involving multiple signaling pathways, including the Notch signaling pathway, RHOA dependent pathway, RET/PTC3 pathway, and VEGFC/FLT4 axis to promote the invasion and metastasis of cancer cells." (PMID 38562021, 2024). "Reactivation of MAPK signalling pathways after RET-blockade with TKIs, including selpercatinib, is a well-described phenomenon, resulting in the potential for TKI resistance and cancer progression." (PMID 38804700, 2024). "All five patients with multiple PCCs completed genetic testing, and 3 (60.0%) tested positive for an LPV/PV in a hereditary cancer gene, all of which were hereditary PGL/PCC genes (RET = 2, VHL = 1)." (PMID 39539798, 2024). "Research in pancreatic cancer shows consistent overexpression of GDNF by both cancer and nerve cells, which acts through the Ret proto-oncogene (RET) receptor and GDNF family receptor (GFR) α1 to attract cancer cells to nerves." (PMID 39518134, 2024). "Pre-clinical modeling studying RET fusion driven cancer cell lines and patient-derived xenograft (PDX) models first confirmed the activity of MKIs through decreased RET autophosphorylation and inhibition of cell proliferation." (PMID 37627175, 2023). "New selective RET inhibitors are under development; one example is TPX-0046, a dual RET/SRC kinase inhibitor with activity in drug-resistant and naïve RET-driven cancer models." (PMID 36980956, 2023). "If we assume all EGFR T790M and RET fusion discovered from NGS in this study can be detected by other cheaper PCR‐based analyses, 30 (50%) patients' cancer will be targetable." (PMID 38140788, 2023). "Several TKIs now have demonstrated activity across cancer types, so called “agnostic” indications, including the TRK inhibitor larotrectinib, the TRK/ROS1 inhibitor entrectinib, and the RET inhibitors selpercatinib and pralsetinib." (PMID 37168365, 2023). "GDNF promotes cancer progression by binding to GDNF family receptors α1-3 and RET proto-oncogene (RET), which initiate the downstream activation of several signaling pathways, including RAS/ERK, MAPK, JNK, and PI3-K/Akt." (PMID 37566075, 2023). "These scores allowed for a more robust interrogation of other vulnerabilities in NEPC using pan-cancer cell lines that mimic features of NEPC and reliance on RET for survival." (PMID 37065756, 2023). "Not only the distribution of RET and PGFRB change in cancer but also the distribution of several other RTKs, affecting the regulation of cancer pathways." (PMID 36890818, 2023). "Other authors describe NEK2, MACC1, REG1A, KIF18A, RET, and TIP60 as possible PM-related cancer genes." (PMID 37629011, 2023). "In general, this novel method holds great potential to improve clinically relevant gene fusion detection for higher applicability of modern cancer therapies targeting ALK, ROS1, RET, and other gene fusions." (PMID 37300660, 2023). "Although reduced cell viability is a similar aspect between different types of cancer, the versatility of AD80 allows it to act on various molecular targets, including S6K, RET, RAF, and p38 MAPK, making it an attractive multitarget compound." (PMID 37568682, 2023). "These rearrangements lead to constitutively ligand-independent RET tyrosine kinase domain (TKD) activation and act as oncogenic drivers in cancer progression." (PMID 37081420, 2023).
cancer (continued). "According to the prediction and molecular docking results presented in this study, erianin shows high potential to interact with molecules like PIK3CA, RET, KIT, ABL1, and FLT3 in cancers, all of which were found to play important roles in cancer progression." (PMID 35372513, 2022). "Pan-cancer drug target RTK fusions also include the moieties of ALK, ERBB2, FGFR1-4, MET, RET, and ROS1 genes." (PMID 36009413, 2022). "The existence of targetable oncogenic mutations was excluded by utilizing the Illumina amplicon cancer panel (TSACP), sequencing 212 regions in 48 cancer-related genes including EGFR, BRAF, KRAS, MET, and RET." (PMID 35039644, 2022). "All the other regions were comprised of multiple genes, including a few known cancer genes according to COSMIC Cancer Gene Census v92: SLC34A2 on 4p15.2, RET on 10q11.21, HSP90AA1 on 14q32.31, and JAK3 on 19p13.11." (PMID 35922826, 2022). "Cabozantinib is used for cancer treatment and inhibits various receptor tyrosine kinases, including VEGFR, MET, RET, KIT, AXL and FLT332." (PMID 35449173, 2022). "TPX-0046 is a dual RET/SRC kinase inhibitor, with activity in drug-resistant and naïve RET-driven cancer models." (PMID 36091144, 2022). "We investigated clinically relevant RTK fusion genes, namely ABL1, ALK, ERBB2, FGFR1-4, NTRK1-3, RET, and ROS1, because they are among the most frequent druggable cancer molecular biomarkers." (PMID 36009413, 2022). "RET is activated through the glial cell line-derived neurotrophic factor (GDNF) family of ligands and has been reported to be activated in several cancer types." (PMID 36142729, 2022). "Sunitinib inhibits PDGFRs, VEGFRs, c-kit, FLT3, CSF-1R and RET and is FDA approved for the treatment of several cancers." (PMID 35629326, 2022). "In an effort to overcome the suboptimal clinical benefit of MKIs in RET-altered cancers, agerafenib (CEP-32496; RXDX-105) was developed as an orally available, ATP-competitive, selective inhibitor of RET and BRAF." (PMID 35957881, 2022). "We examined RET activation following treatment with C3, as well as LOXO-292, a commercially available RET inhibitor currently in clinical trials as an anti-cancer therapy." (PMID 35798698, 2022). "A therapeutic antagonistic monoclonal antibody, which targets GFRAL and inhibits RET signaling by preventing the GDF15-driven interaction of RET with GFRAL on the cell surface, successfully prevented cancer cachexia." (PMID 35379793, 2022). "Despite the evidence supporting an oncogenic role for RET alterations in CRC, the role of RET in this cancer type remains controversial." (PMID 35957881, 2022). "Therefore, multikinase inhibitors (MKIs) that target multiple tyrosine kinase receptors, including RET and those involved in angiogenesis, such as VEGFRs and PDGFRs, were initially used to treat advanced RET-mutated MTC and subsequently other RET-altered cancers." (PMID 36091144, 2022). "Pz-1 potently inhibited proliferation of human cancer cells carrying either RET- or TRKA oncoproteins (IC50 ~ 1 nM), with a negligible effect against RET- and TRKA-negative cells." (PMID 34373541, 2021). "We analysed cell proliferation of RET- and TRKA-positive cancer cells using Pz-1 doses ranging from 0.2 to 100 nM." (PMID 34373541, 2021). "To model RET-dependent oncogenic transformation, we used data from previous work that screened Drosophila GMR-RETM955T and ptc>RETM955T cancer models." (PMID 34520464, 2021). "Cancer significantly upregulated PD-L1 expression through JAK2-STAT1 signaling, and inhibition of RET blocked this effect." (PMID 34885121, 2021). "For instance, the use of small-molecule kinase inhibitors substantially improved treatment-response rates in patients with ALK receptor tyrosine kinase [ALK-], RET- and ROS1-rearranged cancers." (PMID 34585724, 2021). "Analysis demonstrated two known cancer genes (NCOA4 and RET) and a further five candidate cancer genes (LLGL1, LRIG1, LYRM9, ST3GAL6, and TMEM199) were within breakpoint‐containing TADs." (PMID 31943436, 2020).
cancer (continued). "Later on, more targeted drugs have been developed against well-recognized driver kinases activated in cancer due to KGFs, such as those involving ALK, RET, ROS1, NTRK or FGFR39." (PMID 33257674, 2020). "RET fusions are observed in 10% of papillary thyroid cancers, 1–2% of NSCLC cases and other cancer subtypes, including colorectal, pancreatic and breast cancers." (PMID 31598903, 2020). "In this article, we critically review recent findings of RET alterations in human cancers, including both oncogenic and TKI-adapted alterations, targeted therapy of RET-altered cancers, and raise issues that require further studies." (PMID 35582449, 2020). "Remarkable success has been achieved by targeting oncogenic gene fusions including diverse tyrosine kinase inhibitors against fusions involving ALK, ROS1, RET, FGFR1/2/3, and NTRK1/2/3 in non-small-cell lung cancer and across a wide spectrum of cancer types." (PMID 32411236, 2020). "The authors found that RET activation, MAPK pathway activity, and cancer cell migration towards GDNF were increased upon exposure to soluble GFRα1." (PMID 32737575, 2020). "Functional cross-talk of MET with other RTKs, such as EGFR, HER2, HER3, RET or IGF1R, was identified in various cancers as mediating inhibitors resistance." (PMID 31040922, 2019). "In contrast, several agents, such as cabozantinib (VEGFR, MET, RET), ABT-888 (PARP), dabrafenib (BRAF), imatinib (Bcr/Abl), and sunitinib (PDGFR), demonstrated relatively minimal anti-cancer activities." (PMID 31771620, 2019). "As expected, many apoptosis-related genes, involving ARHGEF2, TNFRSF12A, and SFRP2, were hypermethylated in CMT, and some oncogenes in human cancers, HRAS, FAM83H, and RET, were found as hypomethylated." (PMID 31569550, 2019). "Additional biomarkers currently being studied for application in cancer treatment include the PIK3CA, HER2, BRAF, ROS, RET, NRAS, MET, and MEK1." (PMID 29721208, 2018). "Once GFLs bind to GFRA1, it transfers its signals to co-receptor RET which can activate downstream targets like Src kinase, RAS/MAPK, PLCγ, or PI3K/AKT, resulting in cell proliferation, migration and survival in cancer and neuronal cells." (PMID 29617307, 2018). "This rise was due to alterations at a low percentage in genes with proven predictive value in the context of approved anti-cancer drugs (e.g., EGFR, BRAF, ERBB2, BRCA1, BRCA2, RET, ALK) in all cancer types." (PMID 29544535, 2018). "Intriguingly, RET and GFL expression is found even more broadly in cancer cell lines from various tissues, although in vivo correlates of this in primary tumors are not always available and significance in some cases is not yet clear." (PMID 30666215, 2018). "We found potentially druggable fusions across 29 cancer types, with major recurrent druggable targets in PRAD (TMPRSS2, 205 samples), THCA (RET, 33 samples), and LAML (PML–RARA, 16 samples)." (PMID 29617662, 2018). "LOXO-292, another RET TKI has reported tolerability and efficacy in RET-dependent cancers even in progressive BM after alectinib." (PMID 29696132, 2018). "When comparing fusion events with the remainder of the cancer cohort, fusions involving oncogenes such as EGFR, ERBB2, and RET had increased expression." (PMID 29617662, 2018). "Various cancer-related genes were also differentially expressed significantly, including BRAF, BRCA2, VEGFA, VEGFB, RET, PIK3CA, CTNNB1 and GNAS." (PMID 27350898, 2016). "Here, we found a novel RET fusion gene, KIAA1217-RET, and examined the functional differences of RET51 and RET9 protein, fused with KIAA1217 in cancer progression and drug response." (PMID 27150058, 2016). "Next, we used FISH to determine the absolute copy number at loci harboring cancer-relevant genes: ALK, ROS1, MET, BRAF and RET." (PMID 27100738, 2016).
cancer (continued). "This cell line expresses a fusion gene transcript of a tyrosine kinase, RET, and CCDC6, resulting in the aberrant activation of the kinase activity of RET, which serves as a major driving force for carcinogenesis (a cancer driver)." (PMID 25887790, 2015). "In this regard, a retrospective analysis of RET translocations, gene copy number gains and expression from four randomized trials of vandetanib in NSCLC is published in this issue of BMC Cancer." (PMID 25884512, 2015). "In addition, genetic and genomic findings from the cancer-specific Catalogue of Somatic Mutations in Cancer (COSMIC) database were also accessed, while variant classifications were obtained from the databases of the ARUP MEN2/RET program of the Department of Pathology, University of Utah." (PMID 25425582, 2015). "Second, our pipeline was able to recapitulate most known translocation events in cancer (ALK, BRAF, EGFR, FGFR1, 2 and 3, NTRK1, 2 and 3, PDGFRA, PRKCA, RAF1, RET, ROS1)." (PMID 25204415, 2014). "The expression level of six differentially expressed mRNAs (CUL2, HIF1A, RET, JAK1, STAT1, and BCL2) in the cancer pathway and two of their nearby lncRNA pairs (RP11-124O11.2 and lincRNA-TMEM30B-1) was verified by real-time quantitative RT-PCR (qRT-PCR)." (PMID 24672800, 2014). "In our previous studies, we have characterized the conformational landscapes of ABL, EGFR, RET and MET kinases as well as various cancer mutants using MD simulations of the Apo kinase and complexes with ATP and small molecule inhibitors." (PMID 21998754, 2011). "Two kinase inhibitors in clinical trails for several different cancer types are gefitinib (targets EGFR) and vandetinib (antagonist of VEGFR, EGFR and RET-tyrosine kinase)." (PMID 20718987, 2010). "The roles of RET and MET in cancer development and progression are well-known, while the implication of discoidin is a recent finding." (PMID 20955590, 2010). "Furthermore, various somatic genetic rearrangements that lead to chimeric RET oncoproteins are found in sporadic papillary thyroid cancer, non-small-cell lung cancer (NSCLC), and, rarely, other cancer types." (PMID 40725174, 2025). "In those reports, several cancers that were RAS-negative turned out to carry BRAF, TERT or RET/PTC changes, showing that they could have been flagged by a broader gene panel." (PMID 41450928, 2025). "For example, when tested in a Drosophila model of RET‐driven cancer, ZINC98209221 and other lead compounds failed to significantly rescue fly survival." (PMID 40531439, 2025). "Non-germline RET dysregulations in cancer can stem from RET gene rearrangements which lead to the production of a chimeric RET fusion protein, and to constitutive activation of RET promoting cell proliferation and survival." (PMID 38347643, 2024). "Later on, other gatekeeper mutations, such as ALK‐L1196M, ROS1‐L2026M, FGFR1‐V561F/M, FGFR2‐V564F/I, FGFR3‐V555E, FGFR4‐V550L/E/M, RET‐V804L/M, FLT3‐F691I/L, KIT ‐T670I, and PDGFRα‐T674I, were identified in patients with IGST, NSCLC, or other cancers after corresponding TKI treatment." (PMID 39184861, 2024). "Fisher exact analysis was performed to compare RET SSV frequency in cancers with/without a diagnosis of MTC." (PMID 38566816, 2024). "In the absence of the ligand, the RET protein is a single unphosphorylated tyrosine kinase receptor, while in cancer cells, RET proto-oncogene led to the auto-phosphorylation of the tyrosine residues." (PMID 39337252, 2024). "The RET germline tests for the other 10 patients were negative, consistent with a somatic origin for the cancers." (PMID 38566816, 2024).